MEG3 (maternally expressed 3)
Diseases named in the same sentence as MEG3 in open-access papers (continued):
Sharing a sentence is not in itself a finding about the gene and the disease.
tumor (continued). "We therefore used TIMER2.0 to investigate the correlation between MEG3 expression in the TCGA dataset and infiltration across cell types in the tumor microenvironment." (PMID 36231143, 2022). "Among the tumor suppressive effects of MEG3, the most common is that MEG3 down-regulates the downstream miRNA through the effect of molecular sponge, thus upregulates the expression of its target genes." (PMID 36544907, 2022). "Concerning to the results, maternally expressed gene 3 (MEG3), imprinted lncRNA gene, has been proved to be a tumor suppressor gene in HCC." (PMID 36276996, 2022). "It was demonstrated that MEG3 can inhibit the progress of other system neoplasms through increasing the expression of FoxM1, CYLD, and E-cadherin by sponging miR-361-5p, miR-499-5p, and miR-21, respectively." (PMID 36544907, 2022). "In our study, the datasets obtained from TCGA-LIHC showed a unanimous underexpression of MEG3 in HCC as compared to in normal liver, pointing out that MEG3 acts as a bona fide tumor suppressor in HCC." (PMID 36553522, 2022). "MEG3 expression in CC is significantly lowered and this correlated with tumor-mass dimension, late FIGO stage, lymph node metastases, and positive HR⁃HPV." (PMID 35979035, 2022). "More recent investigations of the tumor microenvironment via single-cell technologies have started to show a diverse role of MEG3 depending on its cellular context." (PMID 36231143, 2022). "We reasoned that the presence of MEG3-expressing CAFs drives metastatic potential through reorganization of the extracellular matrix to drive tumor invasion." (PMID 36231143, 2022). "Studies using CRC cancer cell lines have suggested that MEG3 plays an important role as a tumor suppressor gene." (PMID 36077675, 2022). "MEG3 has been proven to have anti-tumor effects, and potential prognostic and clinical significance in various human cancers." (PMID 36551518, 2022). "An increasing number of studies have revealed that MEG3 functions as a tumor suppressor and the possible mechanism involves the modulation of cell growth and apoptosis." (PMID 35565245, 2022). "Upon restoring MEG3 expression or inhibiting methylation, tumor development can be inhibited both in vivo and in vitro." (PMID 36544907, 2022). "MEG3, initially known as a tumor suppressor, is another lncRNA that has received much attention due to its association with the osteogenic differentiation of MSCs, DFCs, and PDL cells." (PMID 35204802, 2022). "For example, overexpression of tumor suppressor lncRNA MEG3 in some cancer cell lines, including lung, squamous cell, and gastrointestinal cancers, prevented cell proliferation and induced apoptosis, thus contributing to patient prognosis." (PMID 35251966, 2022). "MEG3 mediates the hallmarks of cancer through a variety of mechanisms, acting as a tumor suppressor to limit tumor growth." (PMID 36551518, 2022). "Reduced expression of lncRNA maternally expressed gene 3 (MEG3), a tumor-suppressive lncRNA, has been reported in multiple cancers." (PMID 36497250, 2022). "MEG3 promoter methylation is found in most of NSCLC tumor tissues, which mainly contributes to its downregulation." (PMID 34976181, 2022). "A team from the Chinese University of Hong Kong confirmed that MEG3 acts as a tumor suppressor in NPC." (PMID 36544907, 2022). "Subsequent studies showed that MEG3 exerts tumor-inhibitory effects by regulating cell proliferation, migration, invasion, EMT, and chemotherapy sensitivity." (PMID 36544907, 2022).
tumor (continued). "MEG3 is involved in tumor progression in two ways, such as acting as a sponge for miRNA and regulating its targets through transcriptional as well as post-translational regulations." (PMID 36551518, 2022). "The most relevant observation acquired from the study was that there was marked downregulation of MEG3 in tumor compared with normal tissues.In vitroassays showed that upregulation of MEG3 prevented the proliferation, migration, and invasion of tumor cells." (PMID 36530526, 2022). "MEG3 has been reported as a tumor suppressor gene since the reexpression of MEG3 inhibits tumor cell proliferation (; X.)." (PMID 35860793, 2022). "In PC, MEG3 is downregulated and negatively correlated with tumor size, metastasis, and vascular invasion." (PMID 35565245, 2022). "Recently, it was reported that MEG3 enhances the anti-tumor activity of curcumin in gemcitabine-resistant NSCLC cells through the PTEN pathway." (PMID 36544907, 2022). "There are two major categories of lncRs, which are defined as oncogenic lncRs such as MALAT1, HOTAIR, SOX2-OT and H19, and tumor suppressing lncRs such as MEG3, PANDAR, GAS5, and TUG1 according to their pathological features." (PMID 36552560, 2022). "Maternally expressed gene 3 (MEG3), also known as gene trap locus 2 (Gtl2), has been considered as a lncRNA for tumor suppression." (PMID 35480302, 2022). "After cisplatin treatment, the tumor volume, weight and cell necrosis of Hela cells containing knockdown of MEG3 were significantly increased compared to Hela cell, and the administration of antagomiR-21 reversed the effect of knockdown of MEG3." (PMID 36344947, 2022). "Emerging evidence showed that decreased MEG3 expression was related to hypermethylation of the MEG3 promoter in CC tissues, leading to tumor recurrence and short OS." (PMID 36544907, 2022). "Like GAS5, MEG3, an imprinted lncRNA with maternal-specific expression, has been shown to act as a tumor suppressor in several cancers by being in strong functional connection with epigenetic machinery." (PMID 36230680, 2022). "A subsequent study clarified that MEG3 enhances the radiosensitivity of TC cells to 131I by sponging miR-182 and inducing tumor cell apoptosis." (PMID 36544907, 2022). "miR-183 abolished the tumor suppressor function of MEG3 and upregulated the tumor-promoting function of the BRI3 gene." (PMID 35163032, 2022). "An in-depth study showed that high MEG3 expression inhibited tumor invasion and migration by targeting Rac1." (PMID 36544907, 2022). "Remarkably, EC patients had higher levels of known oncogenes (including STAT3 and EZH2) and lower levels of the known tumor suppressor lncRNA MEG3 when compared to normal samples." (PMID 35712514, 2022). "Maternally expressed gene 3 (MEG3) is highly expressed in human tissue and has been demonstrated to play as a tumor suppressor." (PMID 36685879, 2022). "Recent studies have also showed that MEG3 plays a role as a tumor suppressor through the miRNA sponge mechanism." (PMID 36544907, 2022). "Consistent with its tumour suppressor role, MEG3 expression levels were significantly decreased in Pca tumour tissues compared with adjacent tissues." (PMID 35159022, 2022). "We observed a significant decrease in the MEG3 expression level in tumor tissues compared with the paired non-tumor tissues (P-value <0.0001)." (PMID 35186192, 2022). "Four out of five samples demonstrate MEG3 expression in CAFs but little expression in tumor cells, suggesting CAFs are the primary cell types expressing MEG3." (PMID 36231143, 2022).
tumor (continued). "In summary, MEG3 plays a tumor suppressor role in various head and neck malignancies through lncRNAs-miRNAs-mRNAs regulatory pathway and some other mechanisms." (PMID 36544907, 2022). "Protective lncRNA MEG3 was regarded as a novel tumor suppressor by inhibiting tumor cell proliferation in many cancers." (PMID 36101743, 2022). "At the same time, nude mice were used for subcutaneous tumour formation to detect the effect of MEG3 in vivo." (PMID 35257481, 2022). "As a member of tumor suppressor lncRNAs, MEG3 is expected to be a new target for tumor diagnosis and treatment." (PMID 36544907, 2022). "Overall, these experimental pieces of evidence suggest that MEG3 is downregulated and acts as a bona fide tumor suppressor in HCC." (PMID 36553522, 2022). "The inconsistent roles of trophoblasts and tumor cells in cell invasion are interesting, and, thus, functional analyses of MEG3 are needed." (PMID 35954272, 2022). "MEG3, a human ortholog of Gtl2, was considered to be a LncRNA tumor suppresser and its re-expression inhibits tumor cell proliferation and colony formation." (PMID 35955961, 2022). "In the interaction with miRNA, MEG3 can regulate multiple miRNAs, and MEG3 plays a major role in tumor suppression as a ceRNA." (PMID 36544907, 2022). "One of the MEG3 (maternally expressed gene 3) gene transcripts, a 1.6 kb lncRNA situated in 14q32, is a very well-known tumor suppressor lncRNA in many cancer types." (PMID 35755302, 2022). "An in-depth study revealed that MEG3 increases the expression of E-cadherin to inhibit tumor cell invasion and EMT by sponging miR-421." (PMID 36544907, 2022). "The lncRNA, maternally expressed gene 3 (MEG3), acts as a tumour suppressor in various cancer types, including liver, lung, nasopharyngeal and stomach cancer." (PMID 35257481, 2022). "Examining miRNA-141 expression in CRC tumours, it was found that there was an inverse relationship with the levels of MEG3 and oxaliplatin resistance." (PMID 35847932, 2022). "To reconcile discordant trends in tumor MEG3 expression obtained by qPCR and RNA-Seq, we surveyed all MEG3 isoforms found in at least 50% of samples in our dataset." (PMID 36231143, 2022). "Second, MEG3 expression is associated with WHO grade of tumor, old age at diagnosis, Karnofsky performance score (KPS), wild-type isocitrate dehydrogenase (IDH), tumor recurrence and overall survival, which is of prognostic value." (PMID 36523500, 2022). "Accordingly, these findings suggest that MEG3 acts as a tumor suppressor in GC through the miRNA sponge mechanism and other pathways." (PMID 36544907, 2022). "The anti-tumor effect of MEG3 in ESCC was related to MEG3-miR-4261 axis regulating the dickkopf-2 (DKK2) and Wnt/β-catenin signaling." (PMID 35645836, 2022). "Various studies have revealed the significance of the tumor-suppressive effect of lncRNA MEG3 in HCC." (PMID 36553522, 2022). "Other research showed that excessive MEG3 expression inhibited the growth, invasion, and tumor angiogenesis of BC by downregulating the AKT signaling pathway." (PMID 36544907, 2022).
tumor (continued). "The downregulation of MEG3 expression levels was validated in a cohort of 12 pRCC tumors and adjacent non-tumor tissues." (PMID 35626699, 2022). "Lower MEG3 expression enhances tumour progression and it is correlated with a high mortality rate and a poor overall survival, while MEG3 overexpression induces apoptosis." (PMID 36428681, 2022). "Maternally expressed gene 3 (MEG3) was first found to be an important tumor suppressor, specifically expressed in lung cancer and hepatocellular carcinoma." (PMID 35720333, 2022). "Recent studies revealed that MEG3 expression decreased in a wide variety of tumors, playing a crucial role as a tumor suppressor." (PMID 36551518, 2022). "A potential reason for the discrepancy between that study’s results and our findings from the TCGA and NYMC dataset is that MEG3 plays unique roles in cell-autonomous mechanisms vs. its contribution to the tumor microenvironment." (PMID 36231143, 2022). "The tumor growth was reduced in the lncRNA MEG3 group, as showed by a significant decrease in tumor weight and volume." (PMID 36005145, 2022). "In triple-negative breast cancer (TNBC), the expression level of MCM3AP-AS1 increased with tumor size, and overexpression of MCM3AP-AS1 led to an increased proliferation rate of tumor cells through downregulation of MEG3." (PMID 35783356, 2022). "Here we also found suppressed Meg3 upon DES exposure which suggestive of contribution of Meg3 in tumor development." (PMID 35676718, 2022). "More interestingly, MEG3 expression was significantly increased and tumor proliferative and invasive potential was decreased in comparison between the GNAS mutant and wild-type groups." (PMID 36010855, 2022). "Consistently, the expression of MEG3 was also remarkably upregulated in the DDP-treated xenograft tumor model in vivo." (PMID 34326697, 2021). "The lncRNA MEG3 was initially found to be a tumor suppressor that can inhibit the proliferation of tumor cells, but has also been found recently to regulate pyroptosis." (PMID 34012408, 2021). "Current evidence indicates that MEG3 serves as a tumor suppressor to regulate the cancer stemness in head and neck cancers." (PMID 34069546, 2021). "In CC cells, MEG3 serves as a prognostic indicator and diagnostic marker, and its expression is seen to be associated with HR-HPV infection, lymph node metastasis, tumor size, and FIGO staging." (PMID 34885213, 2021). "For instance, the lncRNA MEG3 was deactivated in tumor following the rise in CpG methylation in the promoter region." (PMID 34729108, 2021). "It is worth noting that MEG3 expression levels in tumor tissues were also significantly correlated with AJCC stages (Chi square = 17.61, p < 0.01)." (PMID 35201451, 2021). "MEG3, a tumor suppressor gene, has been demonstrated to regulate the proliferation and invasion of various tumor cells." (PMID 34238211, 2021). "Previous research reported dysregulated MEG3 expression in many human malignancies, and MEG3 functions as a tumor suppressor." (PMID 34421993, 2021). "The present study also predicted that MEG3 is potentially valuable in multiple tumours and cancer pathways." (PMID 33499813, 2021). "Studies have shown that 1α, 25-(OH)2D and vitamin D receptor (VDR) in CRC cells stimulate MEG3 expression by directly binding to the promoter of lncRNA MEG3; MEG3 acts as a tumor suppressor by regulating clusterin activity." (PMID 33718238, 2021). "LncRNA MEG3 (MEG3) has been characterized as a tumor suppressive lncRNA in different types of cancer." (PMID 35201451, 2021). "In summary, MEG3 acts as a tumour suppressor in NPC that can promote the autophagy and apoptosis of NPC cells via increasing PTEN through interaction with miR‐21." (PMID 33332708, 2021).
tumor (continued). "(2018) suggested that LncRNA MEG3 can produce an almost 50% decrease in A375 tumor growth through blocking Wnt signaling pathway." (PMID 33718141, 2021). "MEG3 is another tumor-suppressive lncRNA, with a decreased expression in PDAC cell lines and tissues that is associated with an advanced TNM stage and poor prognosis." (PMID 34820419, 2021). "Maternally Expressed 3 (MEG3) is a tumor suppressor that is involved in the occurrence and development of various malignancies, including HCC." (PMID 34758879, 2021). "The xenograft tumor model demonstrates that overexpression of MEG3 inhibits HCC progression and knockdown of MEG3 suppresses aggressiveness of HCC in vivo." (PMID 34895065, 2021). "In these studies, several lncRNAs, including MEG3, Linc0152 and MALAT1, were identified to play a critical role in the regulation of tumor angiogenesis in IH and demonstrated to be associated with the development of IH." (PMID 33430906, 2021). "MEG3 is assumed as tumor suppressor, regulating gene expression via chromatin modification, transcription, and posttranscriptional procession." (PMID 33572862, 2021). "To further confirm this, we detected MEG3 expression in tumor and normal tissues in patients with HCC." (PMID 34895065, 2021). "MEG3 was found to bind to unique genomic regions in and around c-Met gene and inhibit c-Met expression, leading to tumor suppression." (PMID 34439315, 2021). "MEG3 expresses poorly in various primary human tumours and tumour cell lines, and MEG3 inhibits proliferation of tumour cells." (PMID 33332708, 2021). "MEG3 (non-coding RNA maternally expressed gene) functions as a tumor suppressor in CRC by regulating the activity of clusterin, which is stimulated by the binding of vitamin D receptor to its promoter." (PMID 34218809, 2021). "Consistently, tumor weight in the mice of the Lv-sh-MEG3 + DDP treatment group was remarkably greater than that of the Lv-sh-NC + DDP treatment group, suggesting that MEG3 knockdown promoted tumor growth and inhibited DDP chemotherapy sensitivity in vivo." (PMID 34326697, 2021). "RT‐qPCR identified a higher MEG3 expression and lower miR‐21 expression in xenograft tumours from nude mice injected with the oe‐MEG3‐transfected NPC cells, as compared to nude mice with the oe‐NC‐transfected NPC cells (P < .05)." (PMID 33332708, 2021). "We observed that Meg3 overexpression inhibited tumor growth in Apcmin mice, rendering a phenotype similar to that of ApcminmiR-708−/− mice." (PMID 34934045, 2021). "Lu and colleagues observed that MEG3 induction markedly decreased cell growth and colony formation in vitro, and tumor growth and weight in vivo." (PMID 33803619, 2021). "Taken together, these data suggested that DDP-induced pyroptosis suppressed tumor growth and metastasis via MEG3/NLRP3/caspase-1/GSDMD pathway in a xenograft animal model." (PMID 34326697, 2021). "MEG3 is ubiquitously expressed in normal tissue and loss of its expression has been reported in various cancers, suggesting MEG3 can behave as a tumor suppressor." (PMID 34204445, 2021). "Cell viablity, migration, and invasion were combined to evaluate function of MEG3 and target gene in vitro, while tumor growth was for in vivo experiment." (PMID 34895065, 2021). "MEG3 was highlighted as a tumor suppressor lncRNA in BC tissues; abnormally expressed MEG3 can be distinguished in serum." (PMID 34421993, 2021). "Due to the lack of known functional proteins encoded by the small open reading frames of this gene transcript, MEG3 has been considered as a long non-coding RNA (lncRNA) for tumor suppression." (PMID 34069546, 2021). "MEG3 was the first lncRNA to be identified as a tumor suppressor in the inhibition of cancer cell growth." (PMID 34527584, 2021).